CCR1 (C-C motif chemokine receptor 1)
Diseases named in the same sentence as CCR1 in open-access papers (continued):
Sharing a sentence is not in itself a finding about the gene and the disease.
pulmonary fibrosis (8 papers, 2008 to 2025). Chronic progressive interstitial lung disorder characterized by the replacement of the lung tissue by connective tissue, leading to progressive dyspnea, respiratory failure, or right heart failure. "Notably, the binding of CCL3 to CCR1 has been shown to cause fibroblast aggregation in a bleomycin-induced pulmonary fibrosis model, ultimately leading to fibrosis." (PMID 40396273, 2025). "Additionally, the chemokine receptor CCR1, which is well-known for its association with fibroblast migration in pulmonary fibrosis, was also identified." (PMID 40396273, 2025). "The selective interaction of chemokine CCL3 with its receptor, CCR1, is also crucial for thoracic radiation-induced pulmonary fibrosis." (PMID 30915142, 2019). "Taken together, these data reveal the major regulatory role of macrophages in immune cells and predict that CCL5-CCR5/CCR1 may serve as a potential therapeutic target for lung fibrosis." (PMID 37771586, 2023). "Aberrant activation of CCL3/CCR1 orchestrated the influx of inflammatory cells to the injured sites and triggered tissue repair mechanisms, thereby exacerbating the insult and driving pulmonary fibrosis." (PMID 30915142, 2019). "A similar pivotal role of CCR1 was found in another bleomycin-induced lung fibrosis mouse model." (PMID 30915142, 2019). "In conclusion, our findings demonstrate that HHT can effectively prevent and treat SiO2-induced pulmonary fibrosis in mice, primarily by inhibiting the PI3K/AKT/mTOR signaling pathway and CCR1 expression." (PMID 40396273, 2025). "In addition, few publications could show a role of CCR1 in lung injury using models of lung fibrosis, and as far as we know, there is just one publication showing an anti-inflammatory effect of CCR1 pharmacological blockade in a model of lung inflammation triggered by cigarette smoke." (PMID 34203121, 2021). "As CCL8 binds to CCR1 and CCR2, its effects involve the accumulation of CCR1+ inflammatory cells and CCR2+ macrophages and fibrocytes/fibroblasts, which contribute to collagen deposition, indicating a significant role in pulmonary fibrosis." (PMID 39768150, 2024). "However, the predominant role in the development of pulmonary fibrosis in mice is attributed to Ccl3-Ccr5, as the absence of Ccr1 did not impact disease progression and fibrosis." (PMID 39768150, 2024). "In addition, researchers have suggested that, upon successful entry, the N protein may use miR-223 once again to activate C-C motif chemokine receptor 1 (CCR1), the inflammatory chemokine receptor for CCL3 and CCL5, via NF-κB at its replicative stage, in order to enhance lung fibrosis." (PMID 36142450, 2022). "We recently observed that bleomycin-induced intrapulmonary macrophage accumulation and subsequent pulmonary fibrosis was attenuated in CCL3-KO and CCR5-KO mice but not in CCR1 KO mice." (PMID 18776949, 2008).
Sepsis (8 papers, 2007 to 2025). Sepsis is defined as life-threatening organ dysfunction caused by a dysregulated host response to infection. "Conversely, Ccr1-mediated neutrophil accumulation was pathogenic in a model of acute respiratory distress syndrome following pancreatitis and a model of sepsis following bacterial peritonitis." (PMID 22916017, 2012). "We also detected sepsis eQTL involving the most significant disease SNP for Behcet's disease, which we find modulates expression of the chemokine receptor genes CCR1 and CCR3, which are upregulated and downregulated, respectively, in patients with SRS1." (PMID 26917434, 2016). "Furthermore, in sepsis models, Ccr1-knockout (Ccr1-KO) mice demonstrate attenuated lung inflammation and decreased mortality, highlighting the therapeutic potential of targeting the CCL7-CCR1 axis for the treatment of septic ALI." (PMID 40755420, 2025). "In the genes differentially expressed between SRS groups, there was evidence of enrichment for eQTL (χ2 p<0·0001), including for genes previously implicated in the pathogenesis of sepsis and its treatment, such as IL18RAP, CCR1, CCR3, and SIRT1 (appendix 1 pp 17–18 and appendix 2)." (PMID 26917434, 2016). "However, only CCR1 showed upregulation in the diaphragm during sepsis, and this was observed at the 24-hour time point." (PMID 19421418, 2009). "For example, CCR1-/- mice have improved survival in experimental sepsis and the age-related increase in T cell CCR1 may contribute to the observed increased mortality in septicemia in aging." (PMID 18001471, 2007).
gastric cancer (7 papers, 2020 to 2025). A primary or metastatic malignant neoplasm involving the stomach. "Similarly, it was also reported that CCR1 involved CCL7-induced liver metastasis of CRC as well as gastric cancer metastasis." (PMID 35715847, 2022). "In addition, CCR1 and STAT1 are protective factors for gastric cancer." (PMID 35174205, 2022).
leukemia (7 papers, 2021 to 2025). A malignant (clonal) hematologic disorder, involving hematopoietic stem cells and characterized by the presence of primitive or atypical myeloid or lymphoid cells in the bone marrow and the blood. "Finally, although CCR1 antagonists have been tested in clinical trials for the treatment of endometriosis and leukemia, their therapeutic value with respect to ocular diseases has not been investigated." (PMID 37903056, 2023). "Moreover, admixture with CCR1- or CCR5-deficient HSPCs blunted the leukemogenic ability of wild-type mouse-derived LSCs, suggesting that leukemia cell-derived CCL3 acts mainly on CCR1- or CCR5-expressing normal hematopoietic cells in bone marrow to promote leukemogenesis." (PMID 35006395, 2021). "The expression of liver-specific chemokine receptors, such as CCR1, CCR2, and CCR5, on leukemic cells facilitates their homing to the liver, where they acquire leukemia stem cell (LSC)-like properties, including enhanced self-renewal and proliferative capacity." (PMID 40842579, 2025). "Importantly, blockade of both the CCR1 and CCR2 receptors effectively inhibited the extramedullary infiltration of leukemia cells while alleviating hepatosplenomegaly symptoms." (PMID 38779660, 2024).
lung carcinoma (7 papers, 2015 to 2025). "Using an orthotopic lung cancer model, we confirmed that ERβ facilitates LUAD lymph node metastasis through TAN recruitment, and inhibiting neutrophils with anti-Ly6G antibodies or CCR1 antagonists reduced this effect." (PMID 40739091, 2025).
lymphoma (7 papers, 2019 to 2026). A malignant (clonal) proliferation of B- lymphocytes or T- lymphocytes which involves the lymph nodes, bone marrow and/or extranodal sites. "The decreased expression of CCL28 and CXCL17, coupled with the increased expression of CCR1, may be linked to the progression of LGBLEL into lymphoma." (PMID 39451532, 2024). "As in the other lymphoma entities, the CCR1 and CCR4 expression was rarely or weakly detectable." (PMID 35887224, 2022). "Compared to the lymphoma group, the protein quantitative analysis of the LGBLEL group exhibited significantly differentially expressed CCL28, CCR1, CXCL17, HCK, GNB5, NRAS, and VAV2 (p = 0.003, 0.011, 0.001, 0.024, 0.005, 0.019, and 0.031, respectively)." (PMID 39451532, 2024). "CCR1 showed low positively in the acinar and lymphocyte infiltration area of LGBLEL but was highly positively expressed in lymphoma." (PMID 39451532, 2024). "RT-qPCR showed that, compared to the lymphoma group, the LGBLEL group had significantly higher expression of CCL28, CXCL17, HCK, GNB5, NRAS, and VAV2 (p = 0.001, <0.001, <0.001, <0.001, =0.020, <0.001, respectively) and lower expression of CCR1 (p = 0.002)." (PMID 39451532, 2024). "Moreover, the blockade of CCR1 inhibited protumor M2-like macrophage phenotype by decreasing CD206 and IL-10 expression and triggered a favorable anti-lymphoma activity." (PMID 39351239, 2024). "Compared to the lymphoma group, the LGBLEL group exhibited higher expression levels of CCL28, CXCL17, HCK, GNB5, NRAS, and VAV2 (p = 0.001, <0.001, <0.001, <0.001, 0.020, and <0.001, respectively) and lower expression of CCR1 (p = 0.002)." (PMID 39451532, 2024). "Compared to the lymphoma group, the LGBLEL group showed higher expression of CCL28, CXCL17, HCK, GNB5, NRAS, and VAV2 (p = 0.012, 0.005, 0.009, 0.011, 0.008, and 0.003, respectively) and lower expression of CCR1 (p = 0.014)." (PMID 39451532, 2024). "WB revealed that, compared to the lymphoma group, the LGBLEL group exhibited significantly higher expression of CCL28, CXCL17, HCK, GNB5, NRAS, and VAV2 (p = 0.012, 0.005, 0.009, 0.011, 0.008, and 0.003, respectively) and lower expression of CCR1 (p = 0.014)." (PMID 39451532, 2024). "In lymphoma groups, besides the strongly positive expression of CCR1, other indicators were either not expressed or expressed at low levels." (PMID 39451532, 2024). "Studies have indicated that the expression level of CCR1 in MALT lymphomas is higher than that in inflammatory lesions, as well as being higher in high-grade lymphomas such as diffuse large B-cell lymphomas, which seems to be related to the high-grade transformation of lymphomas." (PMID 39451532, 2024). "To investigate whether the dissemination of lymphoma cells is dependent on the expression of chemokine receptors, we examined the expression of the chemokine receptors CXCR3, CCR4, CCR5 and CCR1 in primary cases of ALCL and cHL by immunohistochemistry." (PMID 31581676, 2019).
metastatic tumor (7 papers, 2015 to 2024). "In this model, genetic deletion of CCR1 in mice also reduces the number of MAMs in metastatic tumors and results in the decreased tumor burden." (PMID 30483271, 2018). "Highly elevated expression of chemokine (C-C motif) ligand 5 (CCL5) and its receptors chemokine (C-C motif) receptor (CCR) 1/3/5 are observed in clinical and murine metastatic tumor tissues from epithelial ovarian carcinomas." (PMID 25788271, 2015). "In a pulmonary metastasis model of renal cancer, MAMs increase CCR5 but not CCR1 expression at the late stage of metastatic tumor development (by 21 days after tumor injection) and loss of Ccr5 but not Ccr1 reduces MAM accumulation in metastatic tumors at this time point." (PMID 30483271, 2018). "The interaction between CCR1 and its ligands, such as CCL15 (humans) or CCL9 (mice), facilitates the recruitment of CCR1+ myeloid cells to primary and metastatic tumor sites." (PMID 39795864, 2024). "Despite these encouraging results, a treatment with single chemokine antagonist will not be enough to suppress metastatic tumor growth since even total deletion of CCR1, CCR2, or CCR5 by knockout cannot achieve complete elimination of metastatic tumors in mouse models." (PMID 30483271, 2018). "In these models, blockade of MAM accumulation via genetic deletion of CCR1, CCR2 or CCR5 significantly reduced metastatic tumor burden, suggesting that antagonists for these receptors can be novel therapeutic agents to prevent metastatic tumor development through inhibition of MAM accumulation." (PMID 30483271, 2018).
neuropathy (7 papers, 2018 to 2025). A disorder affecting the nervous system that manifests with pain, tingling, numbness, and/or muscle weakness. "the development of neuropathy, the protein levels of CCR1 and CCR5, which are located on astrocytes and microglial cells, remained the same." (PMID 41153795, 2025). "We found these receptors interesting to study because, to the best of our knowledge, there are only a few studies concerning CCR1 in neuropathy, and there is only one previously published study (by us) on CCR3 involvement in neuropathy." (PMID 36611891, 2022). "The differential effects of CCR1 versus CCR5 activation, as well as the potential impact on opioid analgesia, underscore the complex role of CCL3 in neuropathy." (PMID 41153795, 2025). "Lidocaine treatment reduced neuropathy symptoms by inhibiting HMGB1 and modulating the CCL3/CCR1/CCR5 axis." (PMID 41153795, 2025). "As our studies demonstrated, a significant proportion of CCR1 and CCR3 ligands are upregulated during neuropathic pain development, which suggests the importance of these receptors in the pathogenesis of neuropathy." (PMID 36611891, 2022). "First, our research provided evidence that the majority of CCR1 and CCR3 ligands are altered in the course of neuropathy in mice." (PMID 36611891, 2022). "The observed differences between the analgesic effects of CCR1 and CCR5 antagonists in STZ-induced neuropathy are highly interesting." (PMID 29593735, 2018). "The obtained results suggest CCR1 and CCR5 as new, interesting targets in neuropathy treatment." (PMID 37190544, 2023). "Our results propose CCR1 and CCR5 as being targets for novel polytherapy for neuropathy." (PMID 37190544, 2023). "We observed for the first time that UCB35625 (CCR1/CCR3 antagonist) inhibits pain-like behavior, without influencing the motor dysfunction observed in neuropathy, which confirms its analgesic effectiveness." (PMID 36611891, 2022). "Furthermore, we found that, during the development of neuropathy in our STZ-induced diabetes model, the protein levels of CCR1 and CCR5 are not changed." (PMID 29593735, 2018).
Obesity (7 papers, 2014 to 2023). Accumulation of substantial excess body fat. "The underlying mechanism that induced an immunosuppressive local microenvironment in obesity was the recruitment of MDSCs through the CCL9/CCR1 axis and enhancement of MDSC immunosuppressive function via intracellular fatty acid uptake." (PMID 34650054, 2021). "Notably, increased adipose tissue levels of multiple β-chemokines (CCL2, CCL3, CCL5, CCL7, CCL8, CCL11) and chemokine receptors (CCR1, CCR2, CCR3, CCR5) have been linked with obesity and associated metabolic inflammation." (PMID 28396851, 2017). "In addition, it has been previously shown that obesity triggers a modest change in the expression of CCR3 and no change in that of CCR1." (PMID 24895488, 2014).
periodontitis (7 papers, 2011 to 2025). An acute or chronic inflammatory process that affects the tissues that surround and support the teeth. "Given their roles in immune activation and leukocyte recruitment, HLA-DRB1 and CCR1 emerge as potential biomarker candidates for detection, risk stratification, and therapeutic monitoring in periodontitis, necessitating validation in larger, well-characterized cohorts." (PMID 41347541, 2025). "CCR1 has been reported to be associated with periodontitis using multiple computational tools." (PMID 40728992, 2025). "Inhibition of the CCR1 gene in macrophages of periodontitis may reduce the chemotaxis of local macrophages in the periodontal region, which may contribute to the alleviation of bone destruction caused by periodontitis." (PMID 40728992, 2025). "Inhibition of CCR1 and suppression of osteoclast differentiation can be observed in murine experimental periodontitis." (PMID 40728992, 2025). "A study involving a mouse model of periodontitis induced by infection with Aggregatibacter actinomycetemcomitans showed that CCR1 and CCR5 are important in alveolar bone resorption." (PMID 38139161, 2023). "Similarly, the CCL pathway, which is known to augment the production of IFNG from the CCL5‒CCR1 interaction, was strongly upregulated in periodontitis patients, which supports the higher activity of INFG." (PMID 36329504, 2022). "As both macrophages and Th1 cells can stimulate the formation and activity of bone resorbing osteoclasts through TNF-α and INF-γ production, the axis CCL3/CCR1/CCR5 might be relevant for periodontitis pathogenesis." (PMID 29163477, 2017). "Therefore, in this study we investigated the modulation of experimental periodontitis outcome by the treatment with a specific antagonist of CCR1 and 5 receptors, called met-RANTES." (PMID 21799885, 2011). "The lack of chemokine receptor CCR1+ diminishes inflammatory bone resorption throughout experimental periodontitis in mice." (PMID 40728992, 2025). "Finally, genotypes are described that protect the mice from periodontitis: the SCID mouse, and mice lacking Tlr2/Tlr4, the Ccr1/Ccr5, the Tnf-α receptor p55, and Cathepsin K by attenuating the inflammatory reaction and the osteoclastogenic response." (PMID 29163477, 2017).
Stroke (7 papers, 2013 to 2025). Sudden impairment of blood flow to a part of the brain due to occlusion or rupture of an artery to the brain. "Female MMP-3 KO stroke brains also had decreased expression of blood cell adhesion genes Pecam1 and Icam2, and decreased expression of inflammatory response genes Ccr1, Cxcl1, Mmp9, Il4ra, Il6, and Il1rn." (PMID 39000490, 2024). "Similar analysis of genes in the Disease and Function categories indicated that female MMP-3 KO stroke brains had decreased expression of leukocyte migration genes Ccr1, Pecam1, Mmp9, Ccl6, Icam2, and Ccl11." (PMID 39000490, 2024). "Though the main cytokines and chemokines revealed an attenuated expression in the sub-acute phase following stroke, chemokine receptors CCR1, CCR2 and CCR5 were found to be unaltered following TREM2 knockout." (PMID 23301011, 2013). "The role of CCL9 has not been investigated in stroke, but deficiency of its receptor, CCR1, attenuated neutrophil adherence to vascular endothelium and transmigration to post-ischemic tissues." (PMID 32872405, 2020). "CCL5 may be able to play a neuroprotective role via CCR5 expressed in neurons in the early phase of stroke, while it may worsen neuronal damage by breaking the blood–brain barrier and inducing invasion by inflammatory cells through CCR1 expressed in vascular cells and white blood cells." (PMID 36077361, 2022). "Whereas CCR1, CCR2 and CCR5 expression was found to be unchanged, a reduced gene transcription of the microglial-associated chemokine receptor CX3CR1 was observed after stroke in TREM2-KO mice compared to littermate control mice (12 h: to 79% ±6.7; 7 d: to 50% ±4.6, p≤0.05, n = 5/6 each)." (PMID 23301011, 2013). "Transcripts of chemokine receptors were also increased in the ischemic hemisphere of wildtype control mice, with a peak at 12 h for CCR1 and a peak at 7 d for CCR2, CCR5 and CX3CR1 after stroke." (PMID 23301011, 2013). "As transcriptome sequencing predicated the important function of MAPK pathway in stroke, and previous study has reported that CCL5 can directly initiate M1 polarization and inhibit M2 polarization through the activation of the MAPK pathway via CCR1 and CCR5 receptors." (PMID 41098728, 2025).
diabetes (6 papers, 2008 to 2025). "In T2DM, CCR1 is involved in chronic inflammation, contributing to the progression of diabetes and its complications." (PMID 40045538, 2025). "The involvement of different intracellular pathways in CCR1 function under diabetes undoubtedly should be examined." (PMID 29593735, 2018). "In summary, our behavioral and biochemical studies highlight a crucial role of two MIP-1 family chemokines in neuropathic pain accompanying diabetes and point to a key role of CCR1." (PMID 29593735, 2018). "CCL5 interacts with several chemokine receptors, such as CCR1, CCR3, and CCR5, to mediate its effects, extending to various pathological conditions, including inflammatory diseases, cancer, and metabolic disorders like diabetes." (PMID 39807180, 2025). "In our study, we found that inflammatory suppression instead of controlling the systemic condition of diabetes might be involved in the effect of TNTL, which may particularly exert a beneficial effect on the normalization of the retina environment by targeting MIP1γ/CCR1 axis." (PMID 31331327, 2019).